FBXW4 (F-box and WD repeat domain containing 4)
Description:
Probably recognizes and binds to some phosphorylated proteins and promotes their ubiquitination and degradation. Likely to be involved in key signaling pathways crucial for normal limb development. May participate in Wnt signaling.
Synonyms: FBW4; SHFM3; dactylin; DAC; FBWD4; SHSF3
Tractability: PROTAC: ubiquitination databases record sites on it.
Gene: Protein-coding gene on chromosome 10 (101,610,663 to 101,695,295, reverse strand). Ensembl gene ENSG00000107829.
Subcellular location (Human Protein Atlas): Golgi apparatus
Pathways (Reactome):
Metabolism of proteins: Association of TriC/CCT with target proteins during biosynthesis; Neddylation
Immune System: Antigen processing: Ubiquitination & Proteasome degradation
Gene Ontology:
Molecular function: protein binding
Biological process: embryonic limb morphogenesis; limb development; SCF-dependent proteasomal ubiquitin-dependent protein catabolic process; ubiquitin-dependent protein catabolic process
Cellular component: cytosol; SCF ubiquitin ligase complex; ubiquitin ligase complex
Genetic constraint (gnomAD): Loss-of-function variants: 38 observed, 49.46 expected, observed/expected ratio (o/e) 0.77, 90% interval 0.59 to 1.01. The upper end of that interval is the gene's LOEUF score, 1.01, which puts it in group 4 of 6, group 1 being the genes least tolerant of losing a copy. Missense variants: 670 observed, 642.23 expected, observed/expected ratio (o/e) 1.04, 90% interval 0.98 to 1.11. Synonymous variants: 311 observed, 265.82 expected, observed/expected ratio (o/e) 1.17, 90% interval 1.07 to 1.28.
Homologues: Orthologues: macaque FBXW4 (97% identical), dog FBXW4 (91% identical), pig FBXW4 (91% identical), rat Fbxw4 (82% identical), chimpanzee FBXW4 (73% identical), rabbit FBXW4 (69% identical), mouse Fbxw4 (66% identical), tropical clawed frog fbxw4 (43% identical), zebrafish fbxw4 (40% identical), Drosophila melanogaster CG33969 (16% identical).
Diseases named in the same sentence as FBXW4 in open-access papers:
FBXW4 is named in the same sentence as 15 diseases in open-access papers, as found by Europe PMC text mining. Sharing a sentence is not in itself a finding about the gene and the disease. The quoted sentences say what the papers report.
glioma (5 papers, 2021 to 2024). A benign or malignant brain and spinal cord tumor that arises from glial cells (astrocytes, oligodendrocytes, ependymal cells). "Nonetheless, future research is imperative to decode the intricate signaling pathways involving FBXW4 and to understand its broader clinical ramifications in glioma treatment paradigms." (PMID 39377096, 2024). "Intriguingly, FBXW4 expression inversely related to WHO tumor grades, with the most advanced grade IV gliomas exhibiting the lowest FBXW4 levels, whereas grade II tumors demonstrated the highest." (PMID 39377096, 2024). "Yet, the therapeutic relevance and specific role of FBXW4 in the context of glioma are not well defined." (PMID 39377096, 2024).
breast carcinoma (4 papers, 2013 to 2024). "mRNA levels of FBXW9 and FBXW4 were negatively associated with stroma score (p < 0.001) in breast cancer." (PMID 36982338, 2023). "In addition to these predicted detrimental mutations, a frame shift mutation, E245fs*, was observed in a breast carcinoma patient that would lead to the production of a FBXW4 protein that is lacking the last three WD-40 motifs." (PMID 23658844, 2013).
non-small cell lung carcinoma (3 papers, 2013 to 2022). A group of at least three distinct histological types of lung cancer, including non-small cell squamous cell carcinoma, adenocarcinoma, and large cell carcinoma. "Previous studies found that decreased expression of FBXW4 was correlated with poor survival among non-small-cell lung cancer patients." (PMID 35589867, 2022). "A previous study demonstrated that decreased FBXW4 expression correlated with poor survival of non-small cell lung cancer patients." (PMID 32218799, 2020). "Importantly, expression of FBXW4 correlates with survival of patients with non-small cell lung cancer." (PMID 23658844, 2013). "Furthermore decreased FBXW4 expression correlates with poor survival of non-small cell lung cancer patients." (PMID 23658844, 2013).
acute kidney injury (1 paper, 2022). Sudden and sustained deterioration of the kidney function characterized by decreased glomerular filtration rate, increased serum creatinine or oliguria. "Six hub genes (MDFI, EHBP1L1, FBXW4, MDM4, RALYL, and ESM1) were identified as potentially predictive of an acute kidney injury." (PMID 36313991, 2022). "The expression of ESM1 and RALYL were markedly increased in control samples, while EHBP1L1, FBXW4, MDFI, and MDM4 were markedly increased in acute kidney injury samples." (PMID 36313991, 2022).
lung carcinoma (1 paper, 2013). "Furthermore, when the expression of FBXW4 mRNA in all lung cancers was compared with the expression in normal lung controls there was a significantly lower level of FBXW4 in cancer samples." (PMID 23658844, 2013). "Finally, we wanted to determine if the expression of FBXW4 mRNA could be a prognostic indicator for the survival outcome of human patients with lung cancer." (PMID 23658844, 2013).
metastatic colorectal cancer (1 paper, 2021). "In addition, studies have shown that KIF14, a co-expressed gene positively associated with XRCC2, plays an oncogenic role in numerous cancers, FBXW4, a gene negatively associated with XRCC2, acts as a protective factor in metastatic colorectal cancer." (PMID 34051735, 2021).
uterine cancer (1 paper, 2021). Primary or metastatic malignant neoplasm involving the uterine corpus and/or the cervix. "In comparison, for UCEC, the role is less clear, although the tumorigenic effect of FGFR2 in uterine cancer is evident at high levels of FBXW4 (6D), in line with previous studies reporting mutations that provide constitutive activation of FGFR2 in a subset of endometrial cancer." (PMID 34408236, 2021).
tumor (7 papers, 2013 to 2024). "FBXW4 mutated and lost in human cancers, it acted as a tumor suppressor in pathophysiological processes." (PMID 32308754, 2020). "Consistent with the well-characterized anti-tumor function of FBXW4, our analysis also showed that the expression of FBXW4 was decreased in several cancer types, and was associated with a good prognosis of patients." (PMID 36982338, 2023). "The results revealed that downregulation of FBXW4 favored tumor relapse and that this was correlated with decreased survival in another four independent R2 online databases." (PMID 32218799, 2020). "FBXW4, a constituent of the F-box and WD repeat domain-containing protein family, is recognized for its participation in diverse cellular activities, including those related to tumor dynamics." (PMID 39377096, 2024). "This may explain why FBXW7 functions as a tumor suppressor, while our data revealed that FBXW4 has oncogenic effects in AML." (PMID 32175272, 2020). "Taken together, we hypothesize that FBXW4 may be an unappreciated tumor suppressor in human malignancies by virtue of its ability to regulate the function of critical signaling pathways." (PMID 23658844, 2013). "Taken together, we suggest that FBXW4 may be a novel tumor suppressor that regulates important cellular processes." (PMID 23658844, 2013). "Conversely, lenti-shRNA-mediated knockdown of FBXW4 increased cell proliferation in MDA-MB-231 cells, and promoted MCF7 cell migration as well as tumor growth following orthotopic transplantation into NSG mice." (PMID 37463901, 2023).
cancer (6 papers, 2013 to 2023). A tumor composed of atypical neoplastic, often pleomorphic cells that invade other tissues. "Again we turned to publicly available datasets and examined the frequency of FBXW4 DNA copy number loss/deletion across 719 diverse human cancer cell lines (Sanger Institutes Cancer Genome Project)." (PMID 23658844, 2013). "The finding that somatic mutations found in human cancers are predicted to disrupt critical aspects of FBXW4 function strengthens the possibility that FBXW4 regulates important homeostatic processes." (PMID 23658844, 2013). "To begin to address the possibility that FBXW4 is important in human cancer we examined whether the gene is mutated in human cancers." (PMID 23658844, 2013). "Importantly, we show that FBXW4 locus is commonly deleted, under-expressed and somatically mutated in human cancers." (PMID 23658844, 2013). "Finally, we demonstrate that FBXW4 is mutated, lost and under-expressed in a variety of human cancer cell lines and clinical patient samples." (PMID 23658844, 2013). "By querying available public databases (The Cancer Genome Atlas (TCGA) project and the Catalogue of Somatic Mutations in Cancer (COSMIC) from the Sanger Institute) we found that FBXW4 is somatically mutated in seven of ∼470 tumors that have been sequence, thus far." (PMID 23658844, 2013). "For instance, FBXW4 is lost and downregulated in many cancers, which maybe lead to a poor prognosis." (PMID 34556022, 2021). "Therefore, we also examined the expression levels of FBXW4 mRNA in cancer cell lines that have lost at least one copy of the FBXW4 gene, compared to cell lines where both copies are seemingly intact." (PMID 23658844, 2013). "Furthermore, the Fbxw4 locus is a common site of proviral insertion in a variety of retroviral insertional mutagenesis murine cancer models and Fbxw4 mRNA is highly expressed in the involuting murine mammary gland." (PMID 23658844, 2013). "Thus far, our data indicate that disruption of FBXW4 may be important in both murine proviral insertional mutagenesis studies and in human cancer patients." (PMID 23658844, 2013). "We queried this database and found that the Fbxw4 gene locus was the only locus in the 30 most commonly identified insertion loci that has not been suggested to play a role in cancer or been biochemically characterized." (PMID 23658844, 2013). "In addition, 1 SNP was detected in KMT2C, a BC oncogene, and 9 others were detected in or near 10 genes (SERAC1, DAGLB, MACF1, NVL, FBXW4, FANK1, KCTD4, CAVIN1; ATP6V0A1 and ZBTB20-AS1) previously associated with non-BC cancers." (PMID 35589867, 2022). "The finding that Fbxw4 interacts with a ubiquitin ligase complex and that disruption of this complex may play a role in cancer progression is not an unfounded model." (PMID 23658844, 2013).
FBXW4 also shares sentences with these, for which no sentence is quoted: colorectal tumor (1 paper); Ectrodactyly (1); glomerulosclerosis (1); Hypertension (1); kidney disease (1); renal fibrosis (1).